ID1 (inhibitor of DNA binding 1)
Diseases named in the same sentence as ID1 in open-access papers (continued):
Sharing a sentence is not in itself a finding about the gene and the disease.
acute promyelocytic leukemia (3 papers, 2017 to 2025). An aggressive form of acute myeloid leukemia (AML), characterized by arrest of leukocyte differentiation at the promyelocyte stage, due to a specific chromosomal translocation t(15;17) in myeloid cells. "All-trans retinoic acid can achieve therapeutic effects in acute promyelocytic leukemia (APL) cell lines and primary patient cells by rapidly increasing ID1 expression and downregulating TCF3, leading to G0/G1 cell-cycle arrest." (PMID 41146039, 2025). "Studies have shown that RARα antagonizes E protein activity by inducing transcription of ID1 and ID2 in human acute promyelocytic leukemia cells treated with all-trans-retinoic acid and ID1 and ID3 gene expression in normal human keratinocytes." (PMID 35503250, 2022). "In myeloid malignancies, ID1 and ID2 were lowly expressed in acute promyelocytic leukemia (APL) cells (NB4) and were rapidly induced upon all-trans retinoic acid (ATRA) treatment." (PMID 29190891, 2017).
adenoma (3 papers, 2008 to 2025). A neoplasm arising from the epithelium. "For subsequent timepoints post-TGF-β1, DEGs were mainly observed in Smad4+/+ adenoma organoids and included Skil, Junb, Serpine 1, Ddit4 and Id1." (PMID 40348815, 2025). "Following TGF-β1 exposure, we identified genes with extremes of differential expression by genotype, including reduced Id1 and increased Spp1 gene expression as consistent features in Smad4Δ/Δ murine adenoma organoids." (PMID 40348815, 2025). "In C2 goblet cells, during the process from normal colon to adenoma and from adenoma to carcinoma, several continuously highly expressed genes were found, including DEFA6, SOX9, ID1, L1TD1, CXCL3, and ODC1." (PMID 36944972, 2023). "And the 6 coincident genes significantly enriched in adenoma and carcinoma were DEFA6, SOX9, ID1, L1TD1, CXCL3, and ODC1." (PMID 36944972, 2023). "Despite the repression of expression, Id1 protein abundance and immune-localisation did not appear to be significantly altered between adenoma genotypes." (PMID 40348815, 2025).
Alzheimer disease (3 papers, 2020 to 2023). A progressive, neurodegenerative disease characterized by loss of function and death of nerve cells in several areas of the brain leading to loss of cognitive function such as memory and language. "In Alzheimer’s disease (AD) the overexpression of ID1 triggers the apoptosis of neuron cells by activating hypoxia-inducible factor-1α and increasing the expression of the sonic hedgehog protein." (PMID 37396785, 2023).
atherosclerosis (3 papers, 2022 to 2023). A disease characterized by the build-up of fatty material and calcium deposition in the arterial wall resulting in partial or complete occlusion of the arterial lumen. "Id1 plays an important role in the occurrence and prevention of atherosclerotic plaque and provides a new target for the prevention and treatment of atherosclerosis in the future." (PMID 35049366, 2022). "In summary, as a dominant negative regulator, Id1 plays an important role not only in cell growth, development, cell cycle regulation, and tumor generation but also in EndMT, angiogenesis, re-endothelialization after injury, inflammation, and atherosclerosis." (PMID 35049366, 2022).
bladder tumor (3 papers, 2020 to 2022). "It has been reported that overexpression of ID1 in advanced bladder tumor cells is associated with the expression of mesenchymal markers, and when downregulated by ID-1si-RNA, the cells expressed epithelial markers." (PMID 32244518, 2020). "Regarding the ID family genes, the expression of ID2, ID3, and ID4 but not ID1 was significantly lower in bladder tumors than in normal urothelium." (PMID 35729325, 2022).
brain cancer (3 papers, 2021 to 2024). A primary or metastatic malignant neoplasm affecting the brain. "ID1 is overexpressed in many types of malignancies, such as breast, lung, prostate, cervical, colorectal, liver, and brain cancer." (PMID 37759448, 2023). "In prostate, liver and brain cancer cell lines, ID1 was inhibited in hypoxia in HIF1α-expressing controls, but was consistently reinstated in HIF1α-KD cells." (PMID 34820369, 2021).
colitis (3 papers, 2022 to 2025). Inflammation of the colon. "In contrast, during acute colitis, Bmp2 expression was strongly reduced in WT but not in IFN-γR KO mice, as was the BMP target gene Id1 (b right)." (PMID 40319019, 2025).
colorectal tumour (3 papers, 2008 to 2019). "In order to investigate the relation between colorectal tumour grades and Id-1, EGFR and VEGF, the tumours were divided into three groups: grade I (G I) (n = 10), grade II (G II) (n = 21) and grade III (G III) (n = 15) tumours." (PMID 19014499, 2008). "Next, we used ID1 mRNA in situ hybridization and HES1 immunohistochemistry on serial sections from colorectal tumour tissue to assess whether loss of stringency in CRC resulted in more widespread co‐localization of these pathways." (PMID 28299802, 2017). "Emerging technologies including single-cell transcriptomics could allow us to test our hypothesis and determine whether ID1 is restricted to a CSC subpopulation in the primary colorectal tumor and is pervasively expressed in secondary lesions emerging after completion of chemotherapy." (PMID 31013771, 2019).
diabetes (3 papers, 2013 to 2023). "Compared to control 5‐month‐old male B6;129 littermates, Id1 protein levels increased up to 15‐fold following stz‐induced diabetes." (PMID 31957231, 2020). "Here, we tested this hypothesis by using streptozotocin to induce diabetes in Id1 knockout (KO) mice and WT B6;129 littermates and examining the mice at 3 months." (PMID 31957231, 2020). "EC Id1 expression levels are increased by pharmacological agonists of BMPr1 and PPARα receptors, suggesting that these drugs may be useful in preventing microvascular injury with diabetes through this mechanism." (PMID 31957231, 2020). "Several predicted interactions were observed, many of them encompassing genes involved in the pathogenesis of diabetes, for instance miR-30e targeting IL1A and IRS2, miR-181a targeting IL1A, miR-223 targeting SLC11A2, miR-29b targeting ID1, miR-21 targeting CCL20, and many others." (PMID 24279768, 2013).
endometrial cancer (3 papers, 2007 to 2023). Primary or metastatic malignant neoplasm involving the endometrium (mucous membrane that lines the endometrial cavity). "High Id-1 levels have been shown to be associated with more than 20 types of cancer including breast, prostate, cervical, liver and endometrial cancer." (PMID 19014499, 2008). "employed transcriptome sequencing technology to analyze 5 pairs of endometrial cancer tissues and normal endometrial tissues, revealing downregulation of ID1, IGF1, GDF7, SMAD9, TGF-β, and WNT4 expression alongside upregulation of GDF5, INHBA, and ERBB4 in endometrial cancer." (PMID 38239355, 2023). "High Id-1 levels have also been found to accompany high grade and invasive endometrial cancers." (PMID 19014499, 2008).
Hyperglycemia (3 papers, 2020 to 2023). An increased concentration of glucose in the blood. "Thus, deficiency of ID1 gene increased insulin secretion to protect against hyperglycemia in an animal model." (PMID 32481541, 2020). "Although young Id1 KO mouse kidneys are phenotypically normal, increased expression of senescence‐associated genes in these mice may only lead to pathology following cell stress such as hyperglycemia." (PMID 31957231, 2020). "We found that the combination of nicotine and hyperglycemia increased the activation of Smad2/3 and the expression of its target genes Id1 and Id4 but decreased the activation of Smad1/5/8 and the expression of its target gene Snail." (PMID 37415117, 2023). "The results showed that the combination of nicotine and hyperglycemia significantly decreased the mRNA levels of Id1 and Id4 but increased Snail." (PMID 37415117, 2023). "In conclusion, endothelial Id1 upregulation with hyperglycemia protects against microvascular injury and senescence and subsequent nephropathy." (PMID 31957231, 2020). "Id1 KO results in endothelial injury and expression of senescence markers in response to hyperglycemia with resulting microvascular damage and nephropathy." (PMID 31957231, 2020). "Id1 KO results in hyperglycemia‐induced EC injury leading to decreased microvascular perfusion and characteristic diabetic pathology." (PMID 31957231, 2020). "Using streptozotocin‐induced hyperglycemia in Id1 knockout mice, we demonstrate that Id1 protects against microvascular injury and endothelial cell senescence and subsequent nephropathy." (PMID 31957231, 2020). "The effect of Id1 KO on capillary density following hyperglycemia was determined by fluorescence microangiography 17 to examine perfusion, combined with CD31 staining for capillary density." (PMID 31957231, 2020). "Id1 is expressed in kidney endothelial cells, and levels are increased in response to hyperglycemia." (PMID 31957231, 2020). "This study demonstrates that Id1 protects against hyperglycemia‐induced endothelial injury and senescence." (PMID 31957231, 2020). "We demonstrate that hyperglycemia and oxidative stress increase endothelial Id1 expression." (PMID 31957231, 2020). "Endothelial dysfunction leads to the development of diabetic nephropathy, and so, we hypothesized that endothelial Id1 may help protect against hyperglycemia‐induced microvascular injury and nephropathy." (PMID 31957231, 2020).
invasive breast carcinoma (3 papers, 2004 to 2024). A carcinoma that infiltrates the breast parenchyma. "Furthermore, we report that the expression of the E6 onco-protein of these high-risk HPVs is correlated with Id-1 overexpression in the majority of invasive breast cancer tissue samples." (PMID 18648363, 2008).
iron deficiency (3 papers, 2012 to 2019). "Liver Hamp mRNA, Bmp6 mRNA and Id1 mRNA displayed the expected response to iron overload and iron deficiency." (PMID 22629388, 2012).
malnutrition (3 papers, 2020 to 2022). Inadequate nutrition resulting from poor diet, malabsorption, or abnormal nutrient distribution. "Moreover, animal studies demonstrated that within 2 months, cells stably transfected with ID1 and NF-κB caused aggressive growth of xenograft tumors in nude mice and induced severe malnutrition." (PMID 33442406, 2021).
Nephropathy (3 papers, 2012 to 2023). A nonspecific term referring to disease or damage of the kidneys. "It is conceivable, for instance, that both ID1 and ID3 are upregulated as a protective mechanism against diabetic insults, which may delay but eventually fail to prevent the onset of nephropathy." (PMID 37863933, 2023).
Obesity (3 papers, 2018 to 2023). Accumulation of substantial excess body fat. "However, the same study found that an adipose tissue specific overexpression of ID1 resulted in high fat diet-induced obesity in mice." (PMID 34832860, 2021).
pulmonary fibrosis (3 papers, 2014 to 2026). Chronic progressive interstitial lung disorder characterized by the replacement of the lung tissue by connective tissue, leading to progressive dyspnea, respiratory failure, or right heart failure. "Lung-specific inhibition of ID1/ID3 using adeno-associated viruses expressing short hairpins targeting ID1 and ID3 also reversed pulmonary fibrosis in mice." (PMID 42094605, 2026). "Pharmacological inhibition of ID1/ID3 decreased HLF proliferation, migration and differentiation in vitro and attenuated pulmonary fibrosis in vivo." (PMID 42094605, 2026).
seminoma (3 papers, 2015 to 2025). A radiosensitive malignant germ cell tumor found in the testis (especially undescended), and extragonadal sites (anterior mediastinum and pineal gland). "Intriguingly, ID signatures (ID1, ID2, and ID9) were significantly associated with DNA replication stress exclusively in seminomas, consistent with prior reports implicating replication-associated DNA damage in TGCT pathogenesis." (PMID 40568177, 2025). "Initially during the seminoma to EC transition, BMP signaling is inhibited, indicated by strong downregulation of ID1/3." (PMID 27283990, 2016). "In CIS, seminomas and ECs, expression of BMP8B, BMPR1A /2, SMAD1 /4 and ID1 /2 was detected, while ID3 expression was restricted to ECs." (PMID 26226633, 2015). "In line with this expression profile, ID1 was detectable in the vast majority of CIS, seminomas and ECs by IHC of GCC tissue microarrays (GCC-TMA), showing that in these GCC entities BMP signaling is active." (PMID 26226633, 2015).
acute lymphoblastic leukemia (2 papers, 2025). Leukemia with an acute onset, characterized by the presence of lymphoblasts in the bone marrow and the peripheral blood. "Studies involving Colombian and Hispanic adult patients newly diagnosed with B cell acute lymphoblastic leukemia (B-ALL) indicate that high expression of ID1 may predict an inadequate response to induction treatment and a poor prognosis." (PMID 41146039, 2025). "In adult Hispanic B-cell acute lymphoblastic leukemia (B-ALL), high JCHAIN expression-part of a 3-gene signature with ID1 and ID3-predicts poor induction therapy response and shortened survival, driven by NF-κB pathway hyperactivation." (PMID 41153653, 2025).
adenoid cystic carcinoma (2 papers, 2013 to 2017). A malignant tumor arising from the epithelial cells. "Furthermore, targeting Id1 with Id1-siRNA in adenoid cystic carcinoma (ACCM) mouse models inhibits tumor growth, reduces tumor cell proliferation/invasion and induces apoptosis." (PMID 28122577, 2017). "We first determined the expression levels of Id1 and Id2 in four SGC cell lines: two adenocarcinoma of the salivary gland (HSG and HSY) and two adenoid cystic carcinoma (ACC2 and ACCM) cell lines." (PMID 23517130, 2013).
asthma (2 papers, 2021 to 2023). "Id1‐deficient CD4 T cells ameliorated airway inflammation in an animal model of asthma." (PMID 37867222, 2023). "Lastly, Id1‐deficient CD4 T cells ameliorated airway inflammation in an animal model of asthma." (PMID 37867222, 2023). "Finally, Id1‐deficient Th9 cells ameliorate airway inflammation in an animal model of asthma." (PMID 37867222, 2023). "The expression of Id1 as well as Il9 was significantly increased in CD4 T cells from the asthma‐induced mice, highlighting the physiological significance of Id1." (PMID 37867222, 2023). "In our study, EP300, ID1, ID3, SMAD2, and SMAD5 were DC with a loss of connectivity, whereas SMAD7 exhibited a network connectivity gain due to asthma." (PMID 34257337, 2021). "Furthermore, expression of genes whose expression correlates with asthma, including Il9, Il4, Il13, Ccl11, Ccl24, and Muc5ac, was much lower in recipients of Id1 cKO Th9 cells." (PMID 37867222, 2023). "Finally, to investigate the functional alterations in Id1‐deficient CD4 T cells in vivo, we used an animal model of asthma." (PMID 37867222, 2023). "In addition, Ccl11, Ccl24, and Muc5ac, which correlate with asthma, decreased in Id1 cKO mice." (PMID 37867222, 2023).
astrocytoma (2 papers, 2013). "Similar results have also been described for ID1–3 proteins in astrocytomas, with higher expression levels in tumors than in non-neoplastic white-matter." (PMID 23613880, 2013).
bladder cancer (2 papers, 2021 to 2022). "Cluster M2 was enriched in LG bladder cancer, and M2 highly expressed transcription factors (ID1 and ELF3), thereby regulating epithelial cell development and mediating inflammatory signals." (PMID 35265520, 2022).
chronic myelogenous leukemia (2 papers, 2022 to 2025). "Our research has revealed that the downregulated miR-29b in the demethylating drug decitabine (DAC)-resistant chronic myeloid leukemia cell line (K562/DAC) leads to abnormal upregulation of ID1 and resistance to apoptosis." (PMID 41146039, 2025).
chronic pancreatitis (2 papers, 2004 to 2019). A chronic inflammatory process causing damage and fibrosis of the pancreatic parenchyma. "In addition, Id-1 expression has been observed in small proliferating ducts and in the large ducts without dysplastic changes of chronic pancreatitis, which again indicates the proliferative potential of Id-1." (PMID 15026801, 2004).
colorectal adenocarcinoma (2 papers, 2008 to 2023). The most common type of colorectal carcinoma. "The mRNA level of ID1 was up-regulated in primary CRC tissues compared with normal controls, with fold-changes of 2.727 in the colon adenoma, 3.129 in the rectal adenoma and 2.021 in the colorectal adenocarcinoma." (PMID 37373188, 2023).
COVID-19 (2 papers, 2021 to 2023). A disease caused by infection with severe acute respiratory syndrome coronavirus 2. "A recent study discovered ID1 differential expression in COVID-19 retest-positive patients, demonstrating the potential influence of COVID-19 on ID expression." (PMID 37109540, 2023). "We demonstrated the downregulation of IFITM10, CH25H, NCR3, and KLRK1 and the upregulation of ID1 in the PBMCs from RTP patients compared with that from patients with moderate or severe COVID-19." (PMID 34687295, 2021).
depression (2 papers, 2012 to 2019). "Neuroplasticity is believed to be involved in ADs action, so changes in Id1 gene expression in the brain cortex may be another potential target for further studies concerning ADs and depression." (PMID 22547330, 2012).
diabetic kidney disease (2 papers, 2020 to 2023). Progressive kidney disorder caused by vascular damage to the glomerular capillaries, in patients with diabetes mellitus. "In the top 10 TFs of kidney, we found two TF markers including ID1, a transcriptional inhibitor that has been reported to drive dedifferentiation of kidney epithelial cells, and EGR1, an early growth response protein associated with diabetic kidney disease." (PMID 36762475, 2023).
gastric adenocarcinoma (2 papers, 2017 to 2023). "Deregulated Id-protein expression has been associated with tumor growth, vascularization, invasiveness, metastasis, chemoresistance, and stemness (summarized by Roschger and Cabrele) and increased ID1 expression has been found in gastric adenocarcinoma." (PMID 37460910, 2023).
Glucose intolerance (2 papers, 2012 to 2020). Glucose intolerance (GI) can be defined as dysglycemia that comprises both prediabetes and diabetes. "Previously, it has been reported that ID1-deficient mice are resistant to diet-induced glucose intolerance and insulin resistance." (PMID 32481541, 2020). "Studies in mice suggest that ID1 is a negative regulator of insulin secretion, playing an essential role in the etiology of glucose intolerance, insulin secretory dysfunction, and β-cell dedifferentiation under conditions of increased lipid supply." (PMID 22607048, 2012).